HSFY2 (heat shock transcription factor Y-linked 2)
Synonyms: HSF2L; HSFY; FLJ25453
Tractability: No criterion of Open Targets' tractability assessment is met for any kind of drug.
Gene: Protein-coding gene on chromosome Y (18,731,440 to 18,773,735, reverse strand). Ensembl gene ENSG00000169953.
Subcellular location: Nucleus; Cytoplasm
Subcellular location (Human Protein Atlas): Cytosol; Nucleoplasm
Gene Ontology:
Molecular function: protein binding; sequence-specific double-stranded DNA binding; DNA-binding transcription factor activity, RNA polymerase II-specific; RNA polymerase II cis-regulatory region sequence-specific DNA binding; DNA-binding transcription factor activity; sequence-specific DNA binding
Biological process: regulation of transcription by RNA polymerase II; regulation of DNA-templated transcription
Cellular component: cytosol; nucleoplasm; chromatin; cytoplasm; nucleus
Homologues: Orthologues: rat Hsfy2 (45% identical), mouse Hsfy2 (44% identical), Caenorhabditis elegans hsf-1 (15% identical), Drosophila melanogaster Hsf (14% identical). Paralogues in human: HSFY1 (100% identical), HSFX1 (29% identical), HSFX2 (29% identical), HSFX3 (19% identical), HSFX4 (19% identical), HSF1 (18% identical), HSF2 (17% identical), HSF4 (17% identical), HSF5 (16% identical).
Diseases named in the same sentence as HSFY2 in open-access papers:
HSFY2 is named in the same sentence as 4 diseases in open-access papers, as found by Europe PMC text mining. Sharing a sentence is not in itself a finding about the gene and the disease. The quoted sentences say what the papers report.
colon cancer (1 paper, 2017). "The significant node of Ezh2 and its TFs such as E2f1, Hsfy2, and Nfyb may show the potential therapeutic effect on colon cancer." (PMID 28588641, 2017). "E2f1, Hsfy2, and Nfyb may be therapeutic targets for colon cancer." (PMID 28588641, 2017). "Thus, the TFs of E2f1, Hsfy2, and Nfyb may play key roles in colon cancer and the functions should be further studied." (PMID 28588641, 2017).
hepatocellular carcinoma (1 paper, 2017). A malignant tumor that arises from hepatocytes. "This study provides the first evidence of the expression of Y-linked lincRNA transcripts such as lnc-KDM5D-4:1, lnc-ZFY-1:1, lnc-ZFY-2:1, lnc-RBMY1B-1:1, lnc-RBMY1B-1:4, lnc-USP9Y-1:4, and lnc-HSFY2-3:6 in human hepatocellular carcinoma (HCC)." (PMID 29196750, 2017).
systemic lupus erythematosus (1 paper, 2024). An autoimmune multi-organ disease typically associated with vasculopathy and autoantibody production. "For example, lncRNAs, such as Hotair, LUST, anti-NOS2A, MEG9, SNHG4, TUG1, and NEAT1, have been found to be highly expressed in rheumatoid arthritis, while the expression of lnc-HSFY2–3:3 and lnc-SERPINB9–1:2 is reduced in systemic lupus erythematosus (SLE)." (PMID 38473997, 2024).
HSFY2 also shares sentences with these, for which no sentence is quoted: Azoospermia (1 paper).